DKK1 (dickkopf Wnt signaling pathway inhibitor 1)
Description:
Antagonizes canonical Wnt signaling by inhibiting LRP5/6 interaction with Wnt and by forming a ternary complex with the transmembrane protein KREMEN that promotes internalization of LRP5/6. DKKs play an important role in vertebrate development, where they locally inhibit Wnt regulated processes such as antero-posterior axial patterning, limb development, somitogenesis and eye formation. In the adult, Dkks are implicated in bone formation and bone disease, cancer and Alzheimer disease. Inhibits the pro-apoptotic function of KREMEN1 in a Wnt-independent manner, and has anti-apoptotic activity (By similarity).
Synonyms: Dkk-1; SK
Tractability: Small molecule: it belongs to a druggable protein family. Antibody: a drug acting on it is in phase 2 or 3 trials; its Gene Ontology location is reachable by antibodies, with high confidence; UniProt places it where antibodies can reach, with medium confidence; UniProt predicts a signal peptide or a membrane-spanning region. PROTAC: a small molecule that binds it is known. Other modalities: a drug acting on it is in phase 2 or 3 trials.
Target class: Secreted protein
Gene: Protein-coding gene on chromosome 10 (52,314,281 to 52,318,042, forward strand). Ensembl gene ENSG00000107984.
Subcellular location: Secreted
Pathways (Reactome):
Signal Transduction: Negative regulation of TCF-dependent signaling by WNT ligand antagonists; TCF dependent signaling in response to WNT
Developmental Biology: POU5F1 (OCT4), SOX2, NANOG repress genes related to differentiation
Disease: Signaling by LRP5 mutants
Gene Ontology:
Molecular function: co-receptor binding; low-density lipoprotein particle receptor binding; protein binding; receptor antagonist activity; growth factor activity
Biological process: negative regulation of canonical Wnt signaling pathway; negative regulation of cardiac muscle cell differentiation; negative regulation of mesodermal cell fate specification; negative regulation of SMAD protein signal transduction; negative regulation of transcription by RNA polymerase II; negative regulation of Wnt signaling pathway; negative regulation of Wnt-Frizzled-LRP5/6 complex assembly; positive regulation of gene expression; positive regulation of JNK cascade; regulation of endodermal cell fate specification; regulation of receptor internalization; endocardial cushion development; heart induction; heart valve development; learning or memory; limb development; negative regulation of apoptotic process; negative regulation of ossification; positive regulation of Wnt signaling pathway, calcium modulating pathway; positive regulation of Wnt signaling pathway, planar cell polarity pathway; regulation of dopaminergic neuron differentiation; regulation of neuron apoptotic process; synapse pruning; motor learning; negative regulation of neuron projection development; and 5 more
Cellular component: extracellular region; plasma membrane; early endosome membrane
Genetic constraint (gnomAD): Loss-of-function variants: 18 observed, 24.23 expected, observed/expected ratio (o/e) 0.74, 90% interval 0.51 to 1.1. The upper end of that interval is the gene's LOEUF score, 1.1, which puts it in group 4 of 6, group 1 being the genes least tolerant of losing a copy. Missense variants: 335 observed, 352.41 expected, observed/expected ratio (o/e) 0.95, 90% interval 0.87 to 1.04. Synonymous variants: 130 observed, 135.23 expected, observed/expected ratio (o/e) 0.96, 90% interval 0.83 to 1.11.
Homologues: Orthologues: chimpanzee DKK1 (99% identical), macaque DKK1 (98% identical), pig DKK1 (91% identical), rabbit DKK1 (89% identical), dog DKK1 (83% identical), mouse Dkk1 (83% identical), rat Dkk1 (82% identical), guinea pig DKK1 (68% identical).
Diseases named in the same sentence as DKK1 in open-access papers:
DKK1 is named in the same sentence as 396 diseases in open-access papers, as found by Europe PMC text mining. Sharing a sentence is not in itself a finding about the gene and the disease. The quoted sentences say what the papers report.
breast carcinoma (161 papers, 2007 to 2026). "High levels of DKK-1 are associated with osteolytic damage in multiple myeloma and breast cancer, whereas a reduction in sclerostin is linked to osteoblastic repair in prostate cancer." (PMID 40426987, 2025). "In breast cancer, CAFs expressing Dickkopf‐1 (DKK1)—a Wnt/β‐catenin inhibitor linked to disease progression—attenuate NK cell activation and cytotoxicity by downregulating AKT/ERK/S6 phosphorylation." (PMID 41164803, 2025). "In fact, in breast cancer, DKK1 expressed by cancer-associated fibroblasts and bone cells suppressed NK cells’ anti-cancerous activity." (PMID 41149482, 2025). "Elevated levels of Dickkopf-1 (DKK1), a soluble inhibitor of the Wnt/β-catenin pathway, are associated with poor prognosis in patients with breast cancer." (PMID 39885132, 2025). "DKK1 has been reported to be highly expressed in various malignant tumors, such as breast cancer, esophageal cancer, and pancreatic cancer, and is associated with poor prognosis." (PMID 38525111, 2024). "In examining the potential utility of the SERM T6I-29-1A in Y537S ESR1 mutant breast cancers, this study revealed a potential new method to modulate DKK1, a paracine factor associated with metastatic progression in many cancers." (PMID 38978585, 2024). "In this study, low expression of DKK1 was significantly associated with adverse breast cancer specific survival." (PMID 38036593, 2023). "DKK-1, a Wnt signaling inhibitor secreted by breast cancer cells, causes CTCs to preferentially metastasize to the bone rather than the lung." (PMID 38129401, 2023). "Low nuclear and cytoplasmic DKK1 expression was significantly associated with adverse breast cancer specific survival (P = 0.002, P = 0.031 respectively)." (PMID 38036593, 2023). "In conclusion, our results indicated that serum DKK-1 was overexpressed in breast cancer and high expression of DKK-1 was associated with poor prognosis." (PMID 25116444, 2014). "In the present study, serum expression level of DKK-1 of 125 patients diagnosed with breast cancer was examined using enzyme-linked immunosorbent assay (ELISA), and the correlations between serum DKK-1 expression and clinicapathological factors were explored." (PMID 25116444, 2014). "Dickkopf-1 is regulated by progesterone in normal endometrial stroma cells, but there is insufficient topical DKK1 expression in normal tissue for it to be linked to the expression profile reported here in breast cancer." (PMID 17245340, 2007). "In this study, we found that Dkk-1 is produced by human osteolytic breast cancer cells in vitro and higher serum levels are associated with the presence of bone metastases in patients with breast cancer." (PMID 17876334, 2007). "The potential role of tumour-derived Dkk-1 in mediating the alterations of osteoblastic and/or osteolytic activity associated with breast cancer however remains to be investigated." (PMID 17876334, 2007). "This work establishes DKK1 as a potential prognostic and diagnostic marker for cohorts of breast cancer patients with poor prognosis." (PMID 17245340, 2007). "This work establishes DKK1 as a potential prognostic and diagnostic marker of aggressive breast cancer types." (PMID 17245340, 2007). "DKK1 is another marker associated with a wide range of tumors, and the dysregulated expression of this gene has been linked to the development and progression of several cancers, including breast cancer." (PMID 38305809, 2024). "It has been demonstrated that high serum levels of DKK1 are associated with poor prognosis among breast cancer patients, since it might reflect an activated status of tumorigenic Wnt/β-catenin signaling." (PMID 32616883, 2020). "In breast and colon cancer, VitD increased dose dependently the expression of the extracellular canonical Wnt inhibitor, DKK-1, that is associated with growth inhibition, showing a protective role of VitD against breast cancer development, progression, and metastasis." (PMID 29462978, 2018).
breast carcinoma (continued). "Indeed, this CpG island has previously been implicated in DKK1 silencing in several types of cancer, including colorectal cancer, gastric cancer, breast cancer, medulloblastoma and leukemia." (PMID 22363428, 2012). "A recent study associates DKK-1 expression in breast cancer with the presence of bone metastases." (PMID 18978943, 2008). "In conclusion, Dkk-1 is secreted by osteolytic human breast cancer cells lines and increased circulating levels are associated with the presence of bone metastases in patients with breast cancer." (PMID 17876334, 2007). "The aim of this study was to determine whether Dickkopf-1 (Dkk-1) expression in breast cancer was associated with bone metastases." (PMID 17876334, 2007). "The aim of this study was to determine whether Dkk-1 expression in breast cancer was associated with the presence of bone metastases." (PMID 17876334, 2007). "Moreover, downregulation of DKK1 has been associated with colorectal- and breast cancer." (PMID 19744316, 2009). "To determine the role of DKK1 in breast cancer progression, we first measured DKK1 serum levels in C57BL/6 mice orthotopically injected with a luminal B, ER+, hormone-resistant PyMT-BO1 cell line into the mammary fat pad (MFP)." (PMID 39885132, 2025). "In sum, our findings position DKK1 as a barrier for efficient anti-tumor immunity in breast cancer through its suppressive effects on NK cell activation and killing efficiency." (PMID 39885132, 2025). "DKK1 levels were significantly increased in tumor-bearing mice, recapitulating findings in breast cancer patients." (PMID 39885132, 2025). "In the meantime, it was demonstrated that ZA (10−4 M) can inhibit dickkopf-1 (DKK1) in breast cancer cells, which affects the Wnt/β-catenin signaling axis." (PMID 40523987, 2025). "In this work, we demonstrate the direct inhibitory effects of DKK1 on NK cell activation and cytotoxicity during breast cancer progression." (PMID 39885132, 2025). "The pro-tumorigenic effects of DKK1 in breast cancer have been mainly attributed to its ability to increase bone resorption, thus creating a favorable environment for tumor dissemination to bone." (PMID 39885132, 2025). "Dickkopf-1 (DKK1) is a Wnt/β-catenin inhibitor, whose levels correlate with breast cancer progression." (PMID 39885132, 2025). "DKK1 overexpression has been observed in various cancers such as esophageal carcinoma, lung cancer, breast cancer, and liver cancer." (PMID 40804038, 2025). "Patient survival analysis using the KM Plotter database revealed that the reduced expression of Cathepsin S (CTSS) and DKK-1 are significantly associated with poor RFS of basal- like breast cancer patients." (PMID 41279138, 2025). "Targeting DKK1 has also been used as a potential treatment for different tumor types, including breast cancer, non-small cell lung cancer (NSCLC), gastric cancer, colorectal cancer, and pancreatic cancer." (PMID 40394415, 2025). "RBM47 has been found to bind to the 3′UTR of DKK1 mRNA and stabilize it, resulting in tumor suppression via Wnt inhibition in breast cancer." (PMID 41516083, 2025). "Our findings indicate the importance of monitoring both systemic and tumor DKK1 levels in breast cancer patients and warrant the exploration of neutralizing DKK1 to achieve an efficient therapeutic response." (PMID 39885132, 2025). "In a breast cancer mouse model, blocking DKK1 with neutralizing antibodies reduced bone metastasis and tumor size, while lung metastasis development was enhanced." (PMID 39107271, 2024). "Serum DKK1 levels were significantly increased 14 days post inoculation, recapitulating the elevated levels observed in breast cancer patients." (PMID 38659818, 2024). "In sum, we find that DKK1 is an important suppressor of NK cell activation and function in breast cancer and that its targeting reduces tumor progression in multiple mouse models." (PMID 38659818, 2024).
breast carcinoma (continued). "The significance of this finding extends beyond cultured breast cancer cell lines because DKK1 is significantly elevated in the blood plasma of ER+ breast cancer patients compared to healthy donor controls." (PMID 38978585, 2024). "Expression of DKK1 can reverse this effect and patients with breast cancer bone metastases that exhibit high levels of DKK1 have better outcomes." (PMID 38455075, 2024). "Together, these data further add to the body of evidence that DKK1 protein levels are elevated ER+ breast cancer patients compared to healthy controls." (PMID 38978585, 2024). "Previous in vitro studies mostly investigated DKK-1 and statins’ correlation in cancer research and found statin-mediated downregulation of DKK-1 protein in endothelial and breast cancer cell lines." (PMID 38541234, 2024). "Univariate regression analysis revealed that Dkk1 levels in mammary carcinoma tissues were significantly predicted by its levels in core needle biopsies (OR = 0.421, CI-95%: 0.209–0.679, p < 0.001)." (PMID 38254908, 2024). "The outcomes of 68 matched pre- and post-therapy tissues showed that Dkk1 levels in mammary carcinoma tissues were significantly predicted by levels in core needle biopsies and that Dkk1 expression was reduced in 83% of cases." (PMID 38254908, 2024). "In breast cancer, DKK1 can be stimulated by the upstream RSPO2–RANKL–LGR4–Gαq–β‐catenin pathway, which promotes the recruitment of osteoclast precursor cells and ultimately promotes the bone metastasis of breast cancer tumors." (PMID 38525111, 2024). "In this study, we demonstrate the direct inhibitory effects of DKK1 on NK cell cytotoxicity during breast cancer progression." (PMID 38659818, 2024). "In contrast, overexpression of DKK1 promoted bone formation while inhibiting the development of lung metastases from breast cancer, suggesting a role for the molecule in organ specificity, even within the same tumor entity." (PMID 39107271, 2024). "Considering the promising therapeutic effects of DKK1 neutralization in patients with gastric and endometrial cancer (NCT04363801, NCT03395080), DKK1 targeting should be investigated as a therapeutic option for patients with breast cancer." (PMID 38659818, 2024). "Our findings indicate that DKK1 creates a tumor-supporting environment through the suppression of NK cells in breast cancer." (PMID 38659818, 2024). "We also find DKK1 to be increased in breast cancer patients with progressive bone metastatic disease compared to those with stable disease." (PMID 38659818, 2024). "DKK1 levels correlate with metastatic progression and reduced cytotoxic NK cells in breast cancer patients." (PMID 38659818, 2024). "Women undergoing 12-week physical training after breast cancer treatment showed statistically significant reductions in serum DKK-1 and sFRP-1 concentrations." (PMID 38792313, 2024). "To improve our understanding of the patient-significance of differential DKK1 expression, we profiled DKK1 levels in 108 ER+ breast cancer patient plasma samples compared to 105 matched plasma controls from healthy women." (PMID 38978585, 2024). "Dkk1 protein expression was assessed using immunohistochemistry staining in core needle biopsies and mammary carcinoma specimens." (PMID 38254908, 2024). "A recent study demonstrated that latency-competent cancer (LCC) cells from early-stage human lung and breast carcinoma can enter a quiescence state through the expression of the WNT inhibitor DKK1 and a broad downregulation of ULBP ligands for NK cells." (PMID 39419971, 2024). "To determine the role of DKK1 in breast cancer progression, we first measured DKK1 serum levels in C57BL/6 mice orthotopically injected with luminal B, ER+, hormone-resistant PyMT-BO1 cell line into the mammary fat pad (MFP)." (PMID 38659818, 2024). "Subsequent profiling of circulating DKK1 shows a significant elevation of DKK1 in the plasma of ER+ breast cancer patients versus healthy controls, which increases with tumor stage." (PMID 38978585, 2024).
breast carcinoma (continued). "It is possible that direct pro-tumorigenic effects of DKK1 on breast cancer only occur at the level of the stem cells, which are too few in our model." (PMID 38659818, 2024). "In this study, we demonstrate that high levels of DKK1 in breast cancer creates an immune suppressive microenvironment through direct inhibition of NK cell tumoricidal functions." (PMID 38659818, 2024). "Dickkopf-1 (DKK1) is a Wnt/b-catenin inhibitor, whose levels are increased in breast cancer patients and correlate with reduced overall survival." (PMID 38659818, 2024). "Our findings indicate the importance of monitoring both systemic and tumor DKK1 levels in breast cancer patients and warrants the exploration of neutralizing DKK1 to achieve an efficient therapeutic response." (PMID 38659818, 2024). "Basal-like breast cancer has upregulated MMP7 expression, which has been linked to DKK1 knockdown, a known tumor suppressor in breast cancer." (PMID 39057065, 2024). "Recently, it has been shown that Dickkopf-Related Protein 1 (Dkk-1) secreted by the breast cancer cells circulates to BM/bones where it attracts OCPs to form a PMN by suppressing the LRP5–ß-catenin–Rnasek axis." (PMID 36890825, 2023). "PRMT5 regulates breast cancer cell growth through epigenetic silencing of DKK1 and DKK3, which are WNT/β-CATENIN pathway antagonists, thus resulting in up-regulation of WNT/β-CATENIN proliferative signaling." (PMID 37924099, 2023). "Screening the secretome of breast cancer stem cells (BCSCs) revealed that dickkopf-related protein 1 (DKK1) reduced the stem cell phenotype by inhibiting Wnt signaling in metastatic cancer cells." (PMID 37369681, 2023). "It is reported that serum DKK-1 levels are higher in patients with bone metastasized breast cancer than at other metastatic sites." (PMID 40226410, 2023). "In breast cancer metastasis, DKK1 is a serum marker that promotes breast cancer bone metastasis by regulating the WNT signaling pathway." (PMID 37007021, 2023). "ET-1 and DKK-1 are well-known markers of bone metastases that induce osteoblastic or osteolytic lesions, respectively, in breast cancer patients resulting in the poor mechanical stability of the bone." (PMID 40226410, 2023). "It was further determined that BCSCs secreted DKK1 to diminish the stemness of breast cancer cells by inhibition of canonical WNT signaling." (PMID 35296660, 2022). "DKK1 is methylated in several cancers, including glioblastoma, renal cell carcinoma, hepatic fibrosis, and breast cancer." (PMID 35625973, 2022). "Serum DKK1 expression levels in 89 breast cancer patients were found to be significantly higher than those in the healthy control group, and the discrepancy was even more evident in patients with bone metastasis." (PMID 35355709, 2022). "The therapeutic potential of pharmacological DKK1 inhibition in breast cancer metastasis was further evaluated." (PMID 35296660, 2022). "RBM47 can increase Dkk1 secretion, which in turn inhibits Wnt signaling, thereby reducing the tumorigenic fitness of metastatic breast cancer cells." (PMID 36052258, 2022). "In a preclinical study in a murine model of breast cancer, elevated DKK-1 promoted osteolytic metastases and increased the number of osteoclasts." (PMID 36230523, 2022). "in breast cancer cells is crucial for DKK1 production via activation of Gαq and β-catenin, enabling further breast cancer metastasis into the bones." (PMID 35707461, 2022). "Studies showed that DKK-1 was overexpressed in prostate and breast cancers and in multiple myeloma bone lesions." (PMID 36230523, 2022). "RBM47 increases the stability of Dkk1 mRNA in breast cancer cells through direct binding to the noncoding region at the 3’ end of Dkk1 mRNA." (PMID 36052258, 2022). "In breast cancer, DKK1 stimulates the metastasis of breast-to-bone through regulating WNT signaling pathway." (PMID 35800432, 2022).